TACC3 (transforming acidic coiled-coil containing protein 3)
Diseases named in the same sentence as TACC3 in open-access papers (continued):
Sharing a sentence is not in itself a finding about the gene and the disease.
lung cancer (20 papers, 2011 to 2025). A malignant neoplasm involving the lung. "Overexpression of TACC3 was previously associated with poor prognosis in lung cancer, and its expression levels were associated with clinical outcomes of lung cancer patients." (PMID 36163484, 2022). "Survival analysis using lung cancer patients (n = 1926) in KM Plotter shows significant association of high expression of TACC3 with poor survival (HR = 1.8; p-value < 1e− 16)." (PMID 27956147, 2017). "Overexpression of TACC3 has previously been associated with oncogenic activity, defective DNA repair, and poor survival in breast and lung cancer." (PMID 28179588, 2017). "TACC3 expression is associated with poor prognosis in lung cancer." (PMID 39603208, 2025). "Moreover, Kaplan–Meier (KM) survival analysis†, showed that high expression of TACC3 is significantly associated with poor survival in lung cancer patients." (PMID 27956147, 2017). "Transforming Acidic Coiled-Coil 3 (TACC3) is acknowledged for its canonical role in centrosome-microtubule spindle dynamics, and its deregulation has been linked to a variety of human cancers, including breast, colon, liver and lung cancers." (PMID 26682275, 2015). "Also, high TACC3 has been shown to be strongly associated with poor survival in breast and lung cancer patients." (PMID 26682275, 2015). "The relationship between higher TACC3 expression and poorer tumor differentiation was demonstrated in lung cancer, hepatocellular carcinoma, and cholangiocarcinoma." (PMID 29135996, 2017). "TACC3 has been previously shown to be overexpressed in various cancers, including lung cancer." (PMID 27956147, 2017). "Furthermore, TACC3 has previously been shown to be up-regulated in lung cancer and, based on our computational analysis, is a prognostic lung cancer marker." (PMID 27956147, 2017). "While radiomics technology has been applied to early lung cancer diagnosis and prognostic stratification, there is limited research integrating radiomics and molecular biology to predict specific molecular markers like TACC3, which could guide personalized treatment." (PMID 39603208, 2025). "The level of TACC3 expression in lung cancer tissues was highly elevated as opposed to that in adjoining nontumor normal tissues." (PMID 35855850, 2022). "We identified seven proteins (Amph, Dok3, Ddx17, Mbip, Rim2, Skap2, TACC3, and Usp33) that are predicted to be EGFR interaction partners and/or share interaction partners within the EGFR pathway, and three of these (Amph, Rim2, and TACC3) show increased expression levels in lung cancer." (PMID 27956147, 2017).
lung adenocarcinoma (14 papers, 2015 to 2026). A carcinoma that arises from the lung and is characterized by the presence of malignant glandular epithelial cells. "Notably, emergence of the FGFR3::TACC3 fusion as a resistance mechanism in TKI-treated EGFR-mutated lung adenocarcinoma was associated with a tendency towards SCC-like transdifferentiation." (PMID 39387893, 2025). "Similarly, literature reports that high TACC3 expression is associated with tumor immune cell infiltration and poor prognosis in lung adenocarcinoma patients, serving as an independent prognostic indicator." (PMID 40223054, 2025). "Furthermore, pancancer survival analysis suggested that elevated TACC3 expression predicted poorer OS and RFS in multiple cancers, including pancreatic ductal adenocarcinoma and lung adenocarcinoma." (PMID 40866361, 2025).
prostate carcinoma (13 papers, 2017 to 2025). A carcinoma that arises from epithelial cells of the prostate gland. "Recent studies have shown that TACC3 is over-expressed in prostate cancer, and is associated with tumor progression and poor prognosis." (PMID 37292153, 2023). "Utilizing Wang Lin’s gene knockout technique, it was demonstrated that depletion of TACC3 in prostate cancer cells elicits primary cilia formation, thereby partially reinstating ciliary abundance." (PMID 38887518, 2024). "Overexpression of TACC3 in prostate cancer cells has been shown to promote cell proliferation and migration." (PMID 37292153, 2023). "TACC3, a key centrosomal protein, was upregulated in prostate cancer, and its silencing inhibited tumor growth." (PMID 35271462, 2022). "TACC3 is up-regulated in prostate cancer and it promotes cell growth and differentiation in a number of other cancers." (PMID 33392209, 2020). "Primary cilia are often reduced or entirely lost in cancerous cells, but knockdown of TACC3 resulted restoration of cilia in a human prostate cancer cell-line." (PMID 33392209, 2020). "Furthermore, TACC3 upregulation has prognostic value in solid tumors, including breast, lung, and prostate cancers." (PMID 39603208, 2025). "By contrast, little attention has been paid to the effects on ARNT/TACC3 axis in prostate cancer." (PMID 37292153, 2023). "Overexpression of TACC3 is correlated with tumor aggression and poor prognosis in prostate cancer." (PMID 33968978, 2021). "Furthermore, the effects of TACC3 overexpression on DFS were consistent among different tumor types: hepatocellular carcinoma (HR=3.03, 95% CI=2.06-4.44), gastric cancer (HR=2.29, 95% CI=1.38-3.82), colorectal cancer (HR=2.05, 95% CI=1.13-3.72), and prostate cancer(HR=3.03, 95% CI=1.79-5.00)." (PMID 29088887, 2017).
urothelial carcinoma (13 papers, 2016 to 2025). A malignant neoplasm derived from the transitional epithelium of the urinary tract (urinary bladder, ureter, urethra, or renal pelvis). "Taken together, it is remarkable that most FGFR3::TACC3 fusion carcinomas display either a transitional cell-like morphology (including urothelial carcinoma), a squamous cell phenotype (SCC), or combined features of both." (PMID 39387893, 2025). "However, several studies have pointed out that most of FGFR3::TACC3 fusion–positive tumors represent either SCC or urothelial carcinomas with squamous-like phenotype." (PMID 39387893, 2025). "Nevertheless, the clinical significance and oncogenic potential of TACC3 in human urothelial carcinomas have not been elucidated." (PMID 29358577, 2018).
non-small cell lung carcinoma (12 papers, 2008 to 2025). A group of at least three distinct histological types of lung cancer, including non-small cell squamous cell carcinoma, adenocarcinoma, and large cell carcinoma. "TACC3 expression is upregulated and associated with shorter median survival in patients with non-small-cell lung cancer." (PMID 21113414, 2010). "The transforming acidic coiled-coil-containing protein 3 (TACC3) seems to be a probable prognostic marker and treatment target for non-small-cell lung cancer (NSCLC)." (PMID 35855850, 2022). "In non-small cell carcinoma, the cut-off value of TACC3 was defined as 10%." (PMID 29135996, 2017). "Depletion of TACC3 from cells using small hairpin RNA (shRNA) knockdown or small-molecule targeting reduced mitogenic signaling in non-small cell lung cancer cell lines, suggesting that targeting TACC3 has potential as a new therapeutic approach for non-small cell lung cancer." (PMID 27956147, 2017).
colorectal cancer (10 papers, 2015 to 2025). A primary or metastatic malignant neoplasm that affects the colon or rectum. "Similarly, TACC3 levels significantly increased in late-stage disease, aligning with its previously reported association with tumor progression and poor prognosis in colorectal cancer." (PMID 40791849, 2025). "TACC3, a member of the transforming acidic colied-coil protein family, is found to be overexpressed in colorectal cancer tissues, contributing to increased cell proliferation and cellular senescence." (PMID 40791849, 2025). "TACC3 is highly expressed in a variety of tumors including colorectal cancer, and promotes tumor progression partially by increasing cell proliferation." (PMID 36221072, 2022). "TACC3, which is expressed specifically in colorectal cancer tissue, is reported to have a strong relationship with worse clinical stage, T classification and M classification." (PMID 30341253, 2018). "Our findings are consistent with earlier studies in that TACC3 was specifically expressed in colorectal cancer tissue." (PMID 30341253, 2018). "To investigate the potential role of TACC3 in determining the sensitivity colorectal cancer (CRC) to radiotherapy, we measured cell proliferation, colony formation and apoptosis after knocking down TACC3 expression using specific siRNA." (PMID 30341253, 2018). "Indeed, colorectal cancer cell lines presenting chromosome instability showed high microtubule growth speed that was dependent on the activity of the TACC3-ch-TOG complex." (PMID 26497677, 2015). "Within the PI3K/AKT signaling pathway, TACC3 promotes epithelial-mesenchymal transition and cellular proliferation, linking its overexpression to increased tumorigenesis and cell proliferation in various cancers, such as hepatocellular carcinoma and colorectal cancer." (PMID 39603208, 2025). "In the “Other tumors group” four rearrangements involving BRAF gene were detected (three melanoma: BRAF::CNNM2, BRAF::ERC1, BRAF::MAD1L1 and one pancreatic adenocarcinoma BRAF::SND1), but also one ETV6::NTRK3 (colorectal cancer) and one FGFR3::TACC3 (urothelial cancer)." (PMID 37708140, 2023).
ovarian carcinoma (10 papers, 2005 to 2025). A malignant neoplasm originating from the surface ovarian epithelium. "Intriguingly, two previous studies have reported an increased risk of ovarian cancer in the daughters of mothers with multiple myeloma, raising the possibility that TACC3 is a candidate gene contributing to the familial association of these two diseases." (PMID 15918899, 2005). "When combined, our data suggest that aberrations of TACC genes, and TACC3 in particular, underlie a significant proportion of ovarian cancers." (PMID 15918899, 2005). "Furthermore, we detected constitutional mutations in the TACC3 gene in ovarian cancer patients from the Gilda Radner Familial Ovarian Cancer registry, in the absence of mutations in known predisposition genes." (PMID 15918899, 2005). "In addition, we identified two constitutional mutations in the TACC3 gene in patients with ovarian cancer from the Gilda Radner Familial Ovarian Cancer Registry." (PMID 15918899, 2005). "Impairment of TACC3 expression in ovarian cancer cells leads to blocked microtubule nucleation and impaired spindle assembly." (PMID 39834092, 2025). "The results showed that TACC3 protein was mainly located to the cell membrane and cytoplasm, and the level of TACC3 proteins were significantly higher in ovarian cancer tissues than those in normal tissues." (PMID 33123295, 2020). "In consequence, on the basis of ceRNA mechanism, we successfully constructed novel mRNA-miRNA-lncRNA regulatory networks (TACC3-hsa-miR-425-5p-FUT8-AS1 and CXCR4-hsa-miR-146a-5p-LINC00665/LINC01535) associated with prognosis of ovarian cancer." (PMID 33123295, 2020). "Only high expression of UBE2C, TK1, TACC3 and CXCR4 and low expression of MAOB were proved to be associated with poor prognosis of patients with ovarian cancer, suggesting the five genes were considered to be the key genes in ovarian cancer." (PMID 33123295, 2020). "Gene expression profiling analysis has revealed that TACC3 is up-regulated during the transition of ductal carcinoma in situ to invasive carcinoma of the breast and in ovarian cancer." (PMID 23936413, 2013). "Transgenomics WAVE high performance liquid chromatography (dHPLC) was used to pre-screen the TACC3 gene in constitutional DNA from ovarian cancer patients and their unaffected relatives from 76 families from the Gilda Radner Familial Ovarian Cancer Registry." (PMID 15918899, 2005). "With the evidence from the expression analysis presented above, it would appear that a significant number of ovarian cancers lack TACC3 expression." (PMID 15918899, 2005). "With the prevalence of aberrations in the expression of TACC3 in the ovarian tumor arrays, we screened the coding sequence of the TACC3 gene in 76 ovarian cancer families that do not have mutations in known ovarian predisposition loci, such as BRCA1 and BRCA2." (PMID 15918899, 2005). "Thus, based upon both the location of TACC1 and TACC3 in regions consistently associated with ovarian cancer and SAGE expression data, we have set out to determine the occurrence of alterations of these TACCs in ovarian cancer." (PMID 15918899, 2005). "We further verified the expression of TACC3 and CXCR4 protein in ovarian cancer tissues and normal tissues stained by immunohistochemistry with HPA." (PMID 33123295, 2020). "These techniques have indicated that deletions or rearrangements of 4p16 and 8p11, the loci for TACC3 and TACC1 respectively, commonly occur in 40% of ovarian cancer cell lines and primary tumors from both familial and sporadic cases." (PMID 15918899, 2005). "SAGE (Serial Analysis of Gene expression) analysis further suggests that TACC3 and TACC1 are downregulated in ovarian tumors and ovarian cancer cell lines." (PMID 15918899, 2005). "Based on the ceRNA hypothesis, novel mRNA-miRNA-lncRNA regulatory networks (TACC3-hsa-miR-425-5p-FUT8-AS1 and CXCR4-hsa-miR-146a-5p-LINC00665/LINC01535) in ovarian cancer were successfully constructed." (PMID 33123295, 2020).
ovarian carcinoma (continued). "However, there were few researches focused on the function of TACC3-miR-425-5p and CXCR4-miR-146a-5p/ hsa-miR-150-5p in ovarian cancer." (PMID 33123295, 2020).
acute myeloid leukemia (9 papers, 2021 to 2025). Acute myeloid leukemia (AML) is a group of neoplasms arising from precursor cells committed to the myeloid cell-line differentiation. "Its leukemia-specific role in regulating oncogenic targets such as transforming acidic coiled-coil containing protein 3 (TACC3) underscores its therapeutic potential as a targetable vulnerability in acute myeloid leukemia." (PMID 40986143, 2025). "Moreover, ALKBH5-dependent m6A demethylation of the TACC3 transcript is frequently modified in acute myeloid leukemia (AML), resulting in CSC stemness maintenance." (PMID 37853437, 2023). "A study on acute myeloid leukemia (AML) has shown that ALKBH5 regulated the expression of TACC3 (a transcription factor) in an m6A-dependent manner, which critically influenced leukemic cell transformation and AML development." (PMID 40001461, 2025). "In addition, ALKBH5 is known to post-transcriptionally regulate TACC3 to promote tumorigenesis and cancer stem cell self-renewal in acute myeloid leukemia (AML), whereas the KDM4C-ALKBH5-AXL signaling axis participates in chromatin alterations in AML leukemia stem cells." (PMID 34491904, 2021). "However, in acute myeloid leukemia (AML), TACC3 exerts pro-cancer effects via ALKBH5-catalyzed demethylation." (PMID 36830673, 2023). "In acute myeloid leukemia (AML), ALKBH5 was required to maintain leukemia stem cell self-renewal and promote AML tumorigenesis by regulating the expression of a set of critical genes (AXL and TACC3) at the posttranscriptional level." (PMID 34759347, 2022).
hepatocellular carcinoma (9 papers, 2015 to 2025). A malignant tumor that arises from hepatocytes. "Additionally, TACC3 expression is reportedly correlated with proliferation in hepatocellular carcinoma cells." (PMID 29135996, 2017). "In hepatocellular carcinoma, FAM111B elevates TACC3 expression, thereby activating the PI3K/AKT signaling pathway." (PMID 40390043, 2025).
squamous cell carcinoma (9 papers, 2016 to 2025). A carcinoma arising from squamous epithelial cells. "The FGFR3::TACC3 fusion has been reported in subsets of diverse cancers including urothelial and squamous cell carcinomas (SCC)." (PMID 39387893, 2025). "In a large German study analyzing RNA-based NGS data from 3309 NSCLC patients, 21 FGFR3::TACC3-positive cases (0.63%) were identified, predominantly among male patients with a median age of 69 years, a higher prevalence of squamous cell carcinoma, and favorable responses to immunotherapy." (PMID 41301039, 2025). "The fusion of the fibroblast growth factor receptor 3 (FGFR3) to the transforming acidic coiled-coil 3 (TACC3) was observed independent of the tumor type (five squamous cell carcinomas and two adenocarcinomas)." (PMID 38256374, 2024).
gastric cancer (7 papers, 2017 to 2025). A primary or metastatic malignant neoplasm involving the stomach. "Meantime, the increased expression of TACC3 was associated with extracapsular invasion in gastric cancer, which might be used as an independent predictor of shorter OS." (PMID 29088887, 2017). "In another study, 20% (5/25) of gastric cancer was found to carry the potentially targetable FGFR3-TACC3 (transforming acidic coiled-coil-containing protein 3) fusion." (PMID 38255923, 2024). "Additionally, TACC3 can promote the EMT of gastric cancer cells through the ERK/Akt/cyclin D1 signaling pathway, which is a critical process in the metastasis of mesothelioma." (PMID 40223054, 2025).
nasopharyngeal carcinoma (7 papers, 2017 to 2025). A carcinoma arising from the nasopharyngeal epithelium. "Treatment of rat hippocampal neural progenitor cells with KHS101 can significantly reduce the TACC3 level and inhibit the progression of nasopharyngeal carcinoma." (PMID 38012214, 2023). "Moreover, recurrent UBR5::ZNF423 and FGFR3::TACC3 fusions have been detected in 8.3% and 2.5% of nasopharyngeal carcinomas, another rare virally induced head and neck carcinoma type." (PMID 39387893, 2025).
melanoma (6 papers, 2017 to 2025). A malignant, usually aggressive tumor composed of atypical, neoplastic melanocytes. "Abnormal expression of TACC1 and/or TACC3 is associated with ovarian, breast, melanoma, bladder, non-small-cell lung and prostate cancers." (PMID 33714201, 2021). "There is increasing evidence to suggest that TACC3 is associated with various types of human cancers, including breast, prostate, colorectal, bladder, gastric, ovarian, lung, melanoma, and liver cancer." (PMID 33714201, 2021). "The FGFR3-TACC3 (transforming acidic coiled-coil containing protein 3) fusion protein has been detected in patients with malignant melanoma." (PMID 31619201, 2019).
multiple myeloma (6 papers, 2005 to 2018). "Recently, TACC3 has been demonstrated as a tumor-associated gene involved in the development of cancer of multiple myeloma, lung, bladder, cervix uteri, breast, thyroid gland, and glioblastoma." (PMID 25760075, 2015). "In addition, TACC3 is located within 200 kb of a translocation breakpoint cluster region associated with multiple myeloma, which results in TACC3 upregulation." (PMID 15918899, 2005). "Once again, this sequence was derived from a leukemia cell line, not from a normal tissue counterpart, suggesting that mutations in TACC3 may also be a feature of other hematological malignancies, in addition to the previously documented aberrant expression observed in multiple myeloma." (PMID 15918899, 2005). "Overexpression of TACC3 is proposed as a marker for poor survival rates in multiple myeloma and breast cancer." (PMID 30344944, 2018). "Rearrangement on chromosome 4p16, a region containing TACC3 and FGFR3, is often found in multiple myeloma." (PMID 30344944, 2018).